ATXN3 (ataxin 3)
Diseases named in the same sentence as ATXN3 in open-access papers (continued):
Sharing a sentence is not in itself a finding about the gene and the disease.
Spinocerebellar ataxia type 3 (continued). "Spinocerebellar Ataxia Type 3 (SCA3) also known as Machado-Joseph Disease (MJD) is a polyglutamine neurodegenerative disorder caused by the expansion of a (CAG)n in the ATXN3 gene." (PMID 26331044, 2015). "This is the case for spinal and bulbar muscular atrophy (SBMA), which is caused by long poly-Q stretches in the androgen receptor, and spinocerebellar ataxia type 3 (SCA3), which is caused by mutations of the ataxin-3 gene." (PMID 23448461, 2013). "Autophagy also has a role in clearance of other polyglutamine-expanded proteins, including mutant ataxin-3 that is causing the spinocerebellar ataxia type 3 (SCA3)." (PMID 22518139, 2012). "In a Spinocerebellar Ataxia Type 3 (SCA3) mouse model, these DNAzymes markedly reduced levels of the pathogenic high-molecular-weight ATXN3 protein." (PMID 40533746, 2025). "Spinocerebellar ataxia type 3 (SCA3), an autosomal dominant neurodegenerative disease, is caused by the abnormal expansion of a CAG repeat in ATXN3." (PMID 39000316, 2024). "While existing drugs have demonstrated limited effectiveness, specifically targeting ATXN3, this study identified a promising candidate for spinocerebellar ataxia type 3." (PMID 38233440, 2024). "Spinocerebellar ataxia type 3 (SCA3) is an autosomal dominant neurogenetic disorder characterized by an unstable CAG trinucleotide repeat sequence in the ATXN3 gene." (PMID 39014518, 2024). "As a result, we have developed a medication to treat type 3 spinocerebellar ataxia using phytochemicals that target the ATXN3 protein." (PMID 38233440, 2024). "One notable SV in an essential gene (LOEUF decile 1) was a 130 bp CAG STR expansion in ATXN3 that is known to cause Machado–Joseph Disease31 (MJD, also known as spinocerebellar ataxia type 3)." (PMID 38093003, 2023). "Spinocerebellar ataxia type 3 (SCA3), also known as Machado–Joseph disease, is a rare autosomal dominantly inherited neurodegenerative disease caused by an abnormal polyglutamine expansion within the ataxin-3 (ATXN3) protein." (PMID 37445783, 2023). "Huntington’s disease (HD) and spinocerebellar ataxia type 3 (SCA3, also called Machado-Joseph disease) are caused by extensive polyglutamine (polyQ) expansion of the huntingtin or ataxin-3 protein." (PMID 37545006, 2023). "Spinocerebellar ataxia type 3 is the most common autosomal dominant inherited ataxia worldwide, caused by a CAG repeat expansion in the Ataxin-3 gene resulting in a polyglutamine (polyQ)-expansion in the corresponding protein." (PMID 34716557, 2022). "In order to investigate whether similar selective pressures might also act on the other polyQ, we tested the polyQ stretch of Ataxin-3 (ATXN3) which is associated with the second most common polyQ disease, Spinocerebellar ataxia type 3 (SCA3)." (PMID 34974533, 2022). "Direct mutation in the gene encoding the DUB occurs in Spinocerebellar ataxia type 3 (SCA3) due to CAG-trinucleotide expansion of the gene encoding ATXN3, resulting in polyglutamine expansion of the ATXN3 gene product, which is a deubiquitinase." (PMID 35159365, 2022). "Spinocerebellar ataxia type 3 (SCA3, Machado-Joseph disease) is a rare movement disorder which caused by an abnormal expansion of the polyglutamine (polyQ) tract in the causative ATXN3 protein." (PMID 35478700, 2022). "Amyloid aggregation of human ataxin-3 (ATX3) is responsible for spinocerebellar ataxia type 3, which belongs to the class of polyglutamine neurodegenerative disorders." (PMID 33477953, 2021). "An investigation on a model for Spinocerebellar Ataxia Type 3 (SCA3) revealed a functional role for DNAJB1 in the clearance of mutant polyglutamine (polyQ) protein ataxin-3 aggregates." (PMID 34234816, 2021). "Spinocerebellar ataxia type 3 (SCA3) is a rare neurodegenerative disorder resulting from an aberrant expansion of a polyglutamine stretch in the ataxin-3 protein and subsequent neuronal death." (PMID 33741019, 2021).
Spinocerebellar ataxia type 3 (continued). "Spinocerebellar ataxia type 3 (SCA3), an autosomal dominant cerebellar ataxia caused by abnormal expansion of cytosine‐adenine‐guanine (CAG) repeats in ATXN3 gene (MIM: 109150), is regarded as the most common SCA subtype in China." (PMID 32643267, 2020). "The nuclear localization of Ataxin-3 has also been proved to be necessary in the symptoms in spinocerebellar ataxia type 3 (SCA3) in vivo." (PMID 32982735, 2020). "Machado–Joseph disease (MJD), also known as spinocerebellar ataxia type 3, is the most common of the dominantly inherited ataxias worldwide and is characterized by mutant ataxin-3 aggregation and neuronal degeneration." (PMID 32272938, 2020). "Spinocerebellar ataxias type 3 (SCA3), also known as Machado-Joseph disease, is the most common SCA worldwide and is caused by CAG expansion of the ATXN3 gene." (PMID 33584500, 2020). "Spinocerebellar ataxia type 3 (SCA3), also known as Machado-Joseph disease (MJD), is caused by abnormal trinucleotide (CAG) expansion in the ATXN3 gene which is located in chromosome 14q." (PMID 30833927, 2019). "ALS and spinocerebellar ataxia type-3 (SCA3) can be studied from this protocol, as the disease-causing sarcoma-fused (FUS) and ataxin-3 proteins of the human variant gene can be expressed in the zebrafish cell culture." (PMID 31151179, 2019). "To date, splicing alterations have only been identified for spinocerebellar ataxia type 3 (SCA3) in the ataxin 3 (ATXN3) gene." (PMID 30262848, 2018). "We first examined a role for intracellular astrocytic responses in a Drosophila model for Spinocerebellar ataxia type 3 (SCA3, also known as Machado–Joseph disease), a disease caused by expansion of the polyglutamine (polyQ) stretch in the ATXN3 gene." (PMID 30205834, 2018). "Spinocerebellar ataxia type 3 (SCA3, previously coined Machado-Joseph disease) is a neurodegenerative disease caused by trinucleotide (CAG) repeat expansion in exon 10 of the ATXN3 gene on chromosome 14 (p32)." (PMID 30035006, 2018). "For instance, the ATXN3 gene usually contains 13–41 CAG repeats; more than 55 CAG repeats in the ATXN3 gene are pathogenic and can cause spinocerebellar ataxia type 3 (SCA3), which is a condition characterized by progressive problems with movement." (PMID 28720120, 2017). "Spinocerebellar ataxia type 3 (SCA3), known as Machado-Joseph disease, is an autosomal dominant disease caused by an abnormal expansion of polyglutamine in ATXN3 gene, leading to neurodegeneration in SCA3 patients." (PMID 28676741, 2017). "In vivo pull-down experiments using HEK293 cells showed reduced binding toward the E4B and enhanced binding toward ataxin 3, thus resembling the accumulation of mutant ataxin 3 on p97 in spinocerebellar ataxia type 3 (Fernández-Sáiz and Buchberger, 2010)." (PMID 27990419, 2016). "The existing data are incomplete and limited mainly to spinocerebellar ataxia type 3 (SCA3), known also as Machado-Joseph disease (MJD), which is caused by expansion of CAG repeats in exon 10 of the ATXN3 gene." (PMID 25873774, 2015). "Ataxin-3, the protein responsible for spinocerebellar ataxia type-3, is a cysteine protease that specifically cleaves poly-ubiquitin chains and participates in the ubiquitin proteasome pathway." (PMID 25988170, 2015). "Spinocerebellar ataxia type 3 (SCA3), also called Machado-Joseph disease (MJD), is one of the most common SCAs worldwide and caused by a CAG repeat expansion located in ATXN3 gene." (PMID 26266536, 2015). "Spinocerebellar Ataxia Type 3 (SCA3), also known as Machado-Joseph disease, is an autosomal dominantly inherited neurodegenerative disease caused by an expanded polyglutamine stretch in the ataxin-3 protein." (PMID 23626768, 2013). "Here, we unveil the role of surface hydrophobicity/hydrophilicity in the misfolding of the Josephin domain (JD), a globular-shaped domain of ataxin-3, the protein responsible for the spinocerebellar ataxia type 3." (PMID 23527026, 2013).
Spinocerebellar ataxia type 3 (continued). "Here, we present investigations aimed at providing insight into the effects of surface properties on the Josephin domain (JD) of ataxin-3 (AT-3), the protein responsible for the spinocerebellar ataxia type 3." (PMID 23527026, 2013). "Ataxin-3 was first recognized as the protein implicated in Machado-Joseph disease (MJD), also known as spinocerebellar ataxia type 3." (PMID 22970133, 2012). "Machado-Joseph disease (MJD), also known as spinocerebellar ataxia type 3, is a dominantly inherited late-onset neurodegenerative disorder caused by expansion of polyglutamine (polyQ)-encoding CAG repeats in the MJD1 (ATXN3) gene." (PMID 22888453, 2012). "This chaperone has been found previously in a genetic screen to reduce the neurotoxicity of the poly-glutamine containing protein ataxin 3 associated with spinocerebellar ataxia type 3 (SCA3), a disease that exhibits a similar cytoplasmic aggregation phenotype to the TDP-43 proteinopathies." (PMID 22384095, 2012). "Ataxin-3 (AT3) is a 42 kDa intracellular protein that is responsible for the polyglutamine (polyQ) disease spinocerebellar ataxia type 3, when the length of its polyQ tract exceeds about 50 consecutive residues." (PMID 21533208, 2011). "Machado-Joseph disease (MJD), or spinocerebellar ataxia type 3 (SCA3), is an autosomal dominant neurodegenerative disorder of late onset, which is caused by a CAG repeat expansion in the coding region of the ATXN3 gene." (PMID 22023810, 2011). "Ataxin-3, the disease protein in the neurodegenerative disorder Spinocerebellar Ataxia Type 3 or Machado Joseph disease, is a cysteine protease implicated in the ubiquitin proteasome pathway." (PMID 20865150, 2010). "Machado-Joseph disease (MJD), or spinocerebellar ataxia type 3, is the most common dominantly inherited ataxia worldwide and it is caused by a polyglutamine (polyQ) expansion in ataxin-3 (Atx3), a polyubiquitin-binding protein with ubiquitin protease activity." (PMID 19503814, 2009). "For example, in spinocerebellar ataxia type 3 (SCA3), the RNA-binding protein ATXN3 associates with RNA Pol II and NHEJ core components to facilitate transcription-coupled DSB repair; mutant ATXN3 disrupts this interaction, compromising repair efficiency and promoting disease progression." (PMID 41258079, 2025). "CAG repeat tracts, which may undergo pathogenic expansion in HD and spinocerebellar ataxia type 3 (SCA3), are located in exon 1 of the HTT gene and exon 10 of the ATXN3 gene." (PMID 40171277, 2025). "Spinocerebellar ataxia type 3 (SCA3), also called Machado-Joseph disease, is the most common autosomal dominantly hereditary ataxia disease caused by an expansion of a trinucleotide CAG repeat in the ATXN3 gene." (PMID 39849568, 2025). "Indeed, KPNA3-dependent nuclear localization of ataxin-3 acts as a key event in the pathogenesis of spinocerebellar ataxia type 3, while ablation of KPNA3 in mice results in abnormal sperm morphology and influences male fertility." (PMID 39621428, 2025). "Spinocerebellar ataxia type 3 (SCA3), also known as Machado–Joseph disease (MJD), is a progressive neurodegenerative disease caused by cytosine–adenine–guanine (CAG) repeat expansion of the ATXN3 gene encoding ataxia protein-3." (PMID 40797466, 2025). "Spinocerebellar ataxia type 3, also known as Machado–Joseph disease (MJD), is a neurodegenerative disorder caused by a polyglutamine-coding CAG trinucleotide repeat expansion in the MJD domain protease subfamily member ATXN3." (PMID 38716888, 2024). "In this complex scenario, at first we demonstrated the capability of HspB8 to inhibit the aggregation of the Josephin domain, the structured part of the ataxin‐3 protein (ATX3) that triggers the earliest steps of the expanded ATX3 fibrillation and the onset of the Spinocerebellar Ataxia type 3." (PMID 37243950, 2023).
Spinocerebellar ataxia type 3 (continued). "Spinocerebellar ataxia type 3 (SCA3), a hereditary and lethal neurodegenerative disease, is attributed to the abnormal accumulation of undegradable polyglutamine (polyQ), which is encoded by mutated ataxin-3 gene (ATXN3)." (PMID 34199295, 2021). "Within the MJD family, ATXN3 represents the most well-studied enzyme as it is related to the development of spinocerebellar ataxia type-3, and its established esterase activity might be of patho-physiological relevance." (PMID 33479176, 2021). "Spinocerebellar ataxia type 3 (SCA3) is a hereditary ataxia caused by inheritance of a mutated form of the human ATXN3 gene containing an expanded CAG repeat region, encoding a human ataxin-3 protein with a long polyglutamine (polyQ) repeat region." (PMID 34685571, 2021). "The utility of the protocol was demonstrated on cell cultures from zebrafish that transgenically express disease-causing variants of human fused in sarcoma (FUS) and ataxin-3 proteins, in order to study amyotrophic lateral sclerosis (ALS) and spinocerebellar ataxia type-3 (SCA3), respectively." (PMID 30190267, 2018). "Spinocerebellar ataxia type 3 (SCA3) also known as Machado-Joseph Disease (MJD), is one of nine polyglutamine (polyQ) diseases caused by a CAG-trinucelotide repeat expansion within the coding sequence of the ATXN3 gene." (PMID 23382971, 2013). "MiRNAs have already been shown to play a role, possibly positively influencing neuronal survival, in the modulation of Ataxin-3 (ATXN3) in the polyglutamine disease spinocerebellar ataxia type 3 (SCA3) where the miRNA ban was determined to act down-stream of ATXN-3 toxicity." (PMID 18987751, 2008). "Spinocerebellar ataxia type 3 (SCA3), also known as Machado Joseph Disease, is the most frequent dominant genetic ataxia and it is caused by CAG repeat expansion in the ATXN3 gene which leads to an expanded polyglutamine tract in the encoded ataxin-3 protein." (PMID 40362688, 2025). "Spinocerebellar Ataxia Type 3 (SCA3), also known as Machado–Joseph Disease (MJD), is caused by an expansion of the CAG codons in the exons of the ATXN3 gene, which produces ataxin-3." (PMID 38921455, 2024). "ATXN3 plays significant roles in neurodegenerative disorders, particularly in spinocerebellar ataxia type 3 (SCA3), also known as Machado‐Joseph disease." (PMID 39678489, 2024). "Spinocerebellar ataxia type 3 (SCA3), a neurodegenerative condition caused by a CAG repeat expansion in the ATXN3 gene, leads to progressive ataxia affecting balance, gait, and speech." (PMID 38724973, 2024). "Numerous REDs are caused by CAG repeats, including the huntingtin gene in Huntington’s disease (HD) and Ataxin 3 in spinocerebellar ataxia type 3 (SCA3), with toxicity largely attributed to the aggregation of long polyQ containing proteins." (PMID 36940239, 2023). "For instance, DNAJB1 is involved in the clearance of mutant polyglutamine (polyQ) protein Ataxin-3 aggregates and is suppressed in spinocerebellar Ataxia Type 3 (SCA3)." (PMID 37104008, 2023). "Expansion of the polyQ tract above a threshold of 45–55 residues leads to ataxin-3 self-assembly and triggers spinocerebellar ataxia type 3 (SCA3), also known as Machado–Joseph disease, a highly incapacitating autosomal-dominant neurodegenerative disorder." (PMID 35741099, 2022). "Her lab works on Spinocerebellar ataxia type 3 (SCA3), known also as Machado Joseph disease, caused by CAG triplet expansion in exon 10 of the ATXN3 gene." (PMID 36239357, 2022). "Spinocerebellar ataxia type 3 (SCA3) is characterized by the over-repetitive CAG codon in the ataxin-3 gene (ATXN3), which encodes the mutant ATXN3 protein." (PMID 35163312, 2022). "The neurodegenerative disease spinocerebellar ataxia type 3 (SCA3; also called Machado-Joseph disease, MJD) is a trinucleotide repeat disorder caused by expansion of the CAG repeats in the ATXN3 gene." (PMID 39872157, 2022).
Spinocerebellar ataxia type 3 (continued). "Spinocerebellar ataxia type 3/Machado–Joseph disease (SCA3/MJD) is the most common autosomal dominant cerebellar ataxia worldwide and is caused by a CAG repeat expansion in the ATXN3 gene, which encodes ataxin‐3." (PMID 35478426, 2022). "Spinocerebellar ataxia type 3 (SCA3), also known as Machado–Joseph disease (MJD), is a neurodegenerative, late-onset, genetic disorder caused by the expansion of CAG repeats in the coding region of the ATXN3 gene (>50 in patients)." (PMID 34220448, 2021). "The sequestration of DNA repair proteins into Htt aggregates is similar to a mechanism observed in models of another polyQ protein, Ataxin-3, related to Machado-Joseph disease, also known as spinocerebellar ataxia type 3 (SCA3)." (PMID 33878947, 2021). "Homozygous spinocerebellar ataxia type 3 (SCA3) patients, which have an expanded cytosine‐adenine‐guanine (CAG) repeat mutation in both alleles of ATXN3, are extremely rare." (PMID 32643267, 2020). "As a case study of using RepeatHMM-DB, we evaluate the CAG repeats of ATXN3 for 20 patients with spinocerebellar ataxia type 3 (SCA3) and 5 unaffected individuals, and correctly classify each individual." (PMID 33371889, 2020). "Spinocerebellar ataxia type 3 (SCA3), also known as Machado–Joseph disease, is the most common dominantly inherited form of degenerative ataxia, caused by an expanded CAG repeat in the ATXN3 gene and marked by irreversible decline in motor function already in mid‐life." (PMID 32510847, 2020). "Machado-Joseph disease (MJD), also known as Spinocerebellar ataxia type 3 (SCA3), is an inherited neurodegenerative disease caused by a CAG repeat expansion in the region of the ATXN3 gene and associated with severe clinical phenotype and premature death." (PMID 31071994, 2019). "Machado–Joseph disease (MJD), also referred to as spinocerebellar ataxia type 3 (SCA3/MJD), is an autosomal dominant neurodegenerative disorder caused by a CAG repeat expansion (CAGexp) at ATXN3, the gene that codes for ataxin-3." (PMID 28979235, 2017). "Spinocerebellar ataxia type 3 (SCA3) is another polyQ repeat disease, which is caused by a polyQ-encoding CAG repeat expansion in the gene encoding Ataxin-3." (PMID 28018215, 2016). "Ataxin-3 is responsible for the neurodegenerative disorder Spinocerebellar ataxia type 3 (SCA3), also known as Machado-Joseph disease, which is the most common dominantly inherited ataxia and a member of the polyglutamine disease family." (PMID 25988170, 2015). "Spinocerebellar Ataxia Type 3/Machado-Joseph Disease (SCA3/MJD) is a hereditary neurodegenerative disorder resulting from the expansion of CAG repeats in the ATXN3 gene." (PMID 26331044, 2015). "We have made the unexpected observation that PNKP stably associates with Ataxin-3 (ATXN3), a polyglutamine repeat-containing protein mutated in spinocerebellar ataxia type 3 (SCA3), also known as Machado-Joseph Disease (MJD)." (PMID 25633985, 2015). "ATXN3 belongs to the MJD class of cysteine proteases and is named after spinocerebellar ataxia type 3, a neurodegenerative disease, which is also called MJD." (PMID 25605410, 2015). "Spinocerebellar ataxia type 3 (SCA3), also known as Machado-Joseph disease, is caused by an unstable CAG repeat expansion in the ataxin-3 (ATXN3) gene leading to an expansion of polyglutamines in the C-terminus of the corresponding protein, ataxin-3." (PMID 24865773, 2014). "Machado-Joseph disease (MJD) or Spinocerebellar ataxia type 3 (SCA3) is a dominant fatal inherited disorder of the central nervous system (CNS) caused by overrepetition of the CAG trinucleotide in the coding region of the MJD1/ATXN3 gene, which encodes the ataxin-3 protein (Atx3)." (PMID 25144231, 2014). "Ataxin-3 (Atx3) is a well known polyQ-containing protein; abnormal expansion of the polyQ tract is responsible for spinocerebellar ataxia type 3 (SCA3) or Machado–Joseph disease." (PMID 21625540, 2011).